MCRS1 (microspherule protein 1)
Description:
Modulates the transcription repressor activity of DAXX by recruiting it to the nucleolus. As part of the NSL complex, may be involved in acetylation of nucleosomal histone H4 on several lysine residues. Putative regulatory component of the chromatin remodeling INO80 complex which is involved in transcriptional regulation, DNA replication and probably DNA repair. May also be an inhibitor of TERT telomerase activity. Binds to G-quadruplex structures in mRNA. Binds to RNA homomer poly(G) and poly(U). Maintains RHEB at the lysosome in its active GTP-bound form and prevents its interaction with the mTORC1 complex inhibitor TSC2, ensuring activation of the mTORC1 complex by RHEB. Stabilizes the minus ends of kinetochore fibers by protecting them from depolymerization, ensuring functional spindle assembly during mitosis. Following phosphorylation by TTK/MPS1, enhances recruitment of KIF2A to the minus ends of mitotic spindle microtubules which promotes chromosome alignment. Regulates the morphology of microtubule minus ends in mitotic spindle by maintaining them in a closed conformation characterized by the presence of an electron-dense cap. Regulates G2/M transition and spindle assembly during oocyte meiosis (By similarity). Mediates histone modifications and transcriptional regulation in germinal vesicle oocytes which are required for meiotic progression (By similarity). Also regulates microtubule nucleation and spindle assembly by activating aurora kinases during oocyte meiosis (By similarity). Contributes to the establishment of centriolar satellites and also plays a role in primary cilium formation by recruiting TTBK2 to the mother centriole which is necessary for removal of the CP110 cap from the mother centriole, an early step in ciliogenesis. Required for epiblast development during early embryogenesis (By similarity). Essential for cell viability.
Synonyms: INO80Q; MSP58; ICP22BP; P78; MCRS2
Tractability: PROTAC: UniProt records ubiquitination sites on it; ubiquitination databases record sites on it; its protein half-life has been measured.
Gene: Protein-coding gene on chromosome 12 (49,556,544 to 49,568,145, reverse strand). Ensembl gene ENSG00000187778.
Subcellular location: Nucleus; Nucleus, nucleolus; Cytoplasm; Cytoplasm, cytoskeleton, microtubule organizing center, centrosome; Cytoplasm, cytoskeleton, spindle pole; Chromosome, centromere, kinetochore; Chromosome; Lysosome; Cytoplasm, cytoskeleton, microtubule organizing center, centrosome, centriolar satellite
Subcellular location (Human Protein Atlas): Nucleoplasm
Pathways (Reactome):
Chromatin organization: HATs acetylate histones
DNA Repair: DNA Damage Recognition in GG-NER
Gene expression (Transcription): Formation of WDR5-containing histone-modifying complexes
Metabolism of proteins: UCH proteinases
Gene Ontology:
Molecular function: G-quadruplex RNA binding; poly(G) binding; poly(U) RNA binding; protein binding
Biological process: chromatin remodeling; positive regulation of DNA-templated transcription; positive regulation of protein localization to nucleolus; regulation of cell cycle; regulation of chromosome organization; regulation of DNA replication; regulation of DNA strand elongation; positive regulation of transcription by RNA polymerase II; protein modification process; regulation of telomere maintenance
Cellular component: cytoplasm; histone acetyltransferase complex; Ino80 complex; lysosome; MLL1 complex; NSL complex; nucleolus; nucleoplasm; nucleus; chromosome; dendrite; perikaryon; centriolar satellite; centrosome; spindle pole
Genetic constraint (gnomAD): Loss-of-function variants: 22 observed, 62.34 expected, observed/expected ratio (o/e) 0.35, 90% interval 0.25 to 0.5. The upper end of that interval is the gene's LOEUF score, 0.5, which puts it in group 2 of 6, group 1 being the genes least tolerant of losing a copy. Missense variants: 456 observed, 605.26 expected, observed/expected ratio (o/e) 0.75, 90% interval 0.7 to 0.81. Synonymous variants: 244 observed, 235.68 expected, observed/expected ratio (o/e) 1.04, 90% interval 0.93 to 1.15.
Homologues: Orthologues: pig MCRS1 (99% identical), chimpanzee MCRS1 (99% identical), macaque MCRS1 (99% identical), dog MCRS1 (99% identical), guinea pig MCRS1 (99% identical), rat Mcrs1 (99% identical), mouse Mcrs1 (98% identical), rabbit MCRS1 (91% identical), tropical clawed frog mcrs1 (82% identical), zebrafish mcrs1 (77% identical), Drosophila melanogaster Rcd5 (52% identical), Caenorhabditis elegans mcrs-1 (24% identical).